RAF1 (Raf-1 proto-oncogene, serine/threonine kinase)
Diseases named in the same sentence as RAF1 in open-access papers (continued):
Sharing a sentence is not in itself a finding about the gene and the disease.
melanoma (continued). "Immunoblotting analyses showed that activities of ERKs and Akt were significantly reduced by Sur8 knockdown in all of the melanoma cell lines tested (SK-Mel5, SK-Mel28, A375, G361, and B16-F10), and Sur8 interacted with p110α, Ras, and Raf-1 in B16-F10 cells at the endogenous protein level." (PMID 26384305, 2015). "These melanomas are sensitive to sorafenib, potentially because they signal through Raf-1." (PMID 23085539, 2012). "Mechanisms of drug resistance in melanoma to vemurafenib do not involve mutations in BRAF itself but are associated with a variety of molecular changes including RAF1 or COT gene over expression, activating mutations in RAS or increased activation of the receptor tyrosine kinase PDGFRβ." (PMID 25562798, 2012). "However, we could not demonstrate co-immunoprecipitation of endogenous BRAF with RAF1, or transiently transfected MYC and FLAG tagged RAF1 in PLX4032-treated melanoma cells under conditions in which RAF1 was activated by the drug." (PMID 20149136, 2010). "Recurrent rearrangements in RAF1, which are functionally similar to BRAF fusions, have been found to occur in advanced prostate cancers, gastric cancers, melanomas, and juvenile pilocytic astrocytomas." (PMID 38137485, 2023). "The methylation of Ser/Tyr RAF1 is also regulated by PRMT5 in melanoma cells, where PRMT5 methylates RAF1 at R563, and downregulates MEK1/2-ERk1/2 protein kinases." (PMID 33670008, 2021). "RAF kinase fusions, such as of BRAF or RAF1 (also known as CRAF), have been reported in various tumor types, including prostate cancer, GC, melanoma, and papillary thyroid cancer." (PMID 32411236, 2020). "Increasingly, gene fusions involving various kinases, including ALK, ROS1, BRAF, RAF1, NTRK1, and NTRK3 have been identified within melanomas, and these fusion-positive melanomas often display spitzoid morphology." (PMID 32483240, 2020). "Surprisingly, despite the central role of RAF1 in the MAP kinase pathway, there are only isolated reports of RAF1 (CRAF) fusions in melanomas, and the histopathologic characterizations of these tumors have been limited." (PMID 32123303, 2020). "Five pathways wereenriched for genes in the module d-1 (MAPK1, MITF,RAF1, JAK1, and STAT3):pancreatic cancer (P=5.47E-04), melanoma (P=8.52E-03), melanogenesis (P=1.48E-02),acute myeloid leukemia (P=7.67E-03), and cancer pathways (P=3.69E-03)." (PMID 26840709, 2016). "Next three genes in the order of decreasing cross-talk frequency are NRAS (cf = 41), RAF1 (cf = 38) and PTPN11 (cf = 38)- the genes are known for its aberrant behaviour in melanoma." (PMID 26558755, 2015). "Gene fusions involving RAF kinase genes (BRAF, RAF1, CRAF) have been identified in low-grade tumors of the central nervous system (pilocytic astrocytomas and other low-grade gliomas), gastric cancer, melanoma and prostate cancer." (PMID 26684754, 2015). "Recurrent rearrangements of the RAF kinases, RAF1 and BRAF, were recently reported in a small fraction of prostate cancers, gastric cancers, and melanomas." (PMID 23637631, 2013). "TCGA analysis detected fusions in BRAF and RAF1 kinases in melanomas, but did not report fusions in ALK, ROS1, MET, RET, or NTRK, which are clinically targetable." (PMID 34831002, 2021). "Frequent accompanying mutations in TERTp and CDKN2A were identified, typical for skin primary melanoma, and TMB was not significantly different from primary skin and anus melanoma cases without activating RAF1 fusions." (PMID 32123303, 2020). "Median TMB was 10.2 mut/Mb (range 0–57.4, 35% 10–20, 18% >20), similar to the primary skin and anus melanoma cohort without activating RAF1 fusions (median TMB = 13.8, 19% 10–20, 36% >20; p = 0.1, Mann–Whitney U test)." (PMID 32123303, 2020). "Of the activating RAF1-fusion melanomas, 98% (n = 39) were wild type for BRAF, NRAS, and NF1 genomic alterations (triple wild type) vs. 26% (n = 1843/7079) of the melanoma cohort without RAF1 fusion (p < 0.0001, Fisher’s exact test)." (PMID 32123303, 2020).
melanoma (continued). "In contrast to Spitz tumors with fusions of ALK, NTRK1, and ROS1, which are usually compound with a prominent epidermal component, epidermal involvement in the RAF1-fused melanomas was typically limited or absent." (PMID 32123303, 2020). "Somatic mutations in the oncogene RAF1 are remarkably rare in human cancers; however, in BRAF negative melanomas, targeting RAF1 leads to apoptosis." (PMID 27993549, 2017). "Furthermore, in agreement with reduced ‘RAF’ protein-chaperone association and greater ‘RAF’ denaturation, treatment of the melanoma cells for 6 h with AR42 or with [pazopanib + AR42] reduced the total protein levels of B-RAF and RAF-1." (PMID 28146421, 2017). "Melanoma cell lines can be clustered into three groups by crs(h = 2) top-ranked genes, one with EGFR and RAF1 ranked high exclusively, the other with MAPK1 at top rank, and the third with a mixture of EGFR/RAF1/MAPK1." (PMID 24550933, 2014). "Similarly, oncogenic rearrangements of the RAF kinases, RAF1 and BRAF, have been found in various cancers including pilocytic astrocytoma, melanoma, gastric cancer, and prostate cancer." (PMID 23637631, 2013). "GSK2118436 (a.k.a. dabrafenib) is an ATP-competitive inhibitor of mutant B-Raf, WT B-Raf and WT Raf-1 developed by GlaxoSmithKlein (GSK) in clinic trial (NCT00880321), which examined patients with melanoma, brain metastases, in other solid tumours it was determined to be safe and elicited responses." (PMID 23085539, 2012). "The effects of Raf-1 on the prevention of apoptosis were demonstrated in the D594G/G469E but not BRAF V600E mutant melanoma cells by shRNA knock down of Raf-1." (PMID 23085539, 2012). "For example, combining rapamycin with sorafenib (a multikinase inhibitor that inhibits Raf-1 and B-RAF) synergistically reduces melanoma cell proliferation, and targeting these two types of signaling pathways simultaneously, may be more effective for treating melanoma than using either agent alone." (PMID 36077992, 2022). "However, a recent report showed that existing RAF inhibitors cannot suppress RAF1-fusion-driven signaling pathways, and our study also showed that a melanoma patient harboring MAPRE2-RAF1 fusion did not respond to vemurafenib." (PMID 32411236, 2020). "Moreover, when the Raf-1 siRNA RGD-NP targets human RAF-1 in the melanoma cells, but not the mouse Raf-1 (in blood vessels), the tumor was inhibited by more than 60%." (PMID 29218233, 2017). "NF1-mutant melanomas were significantly associated with non-duplication SV events in two RASopathy genes, RAF1 and SPRED1 (Fisher’s exact, OR = 5.03, 95% CI = 1.46–16.42, P = 4.8 × 10–3), the latter of which has also been identified as a significantly mutated gene exclusive to NF1-mutant melanomas." (PMID 38758740, 2024). "But, whilst mutant NF1 is known to cooperate with RASopathy genes (RASA2, PTPN11, SOS1, RAF1 and SPRED1) in melanoma and although NF1 is found to be frequently mutated (25–30%) in melanomas harbouring wild-type BRAF and NRAS, it is curious that melanoma is not a tumour type associated with NF1." (PMID 28637487, 2017). "Our studies with melanoma tumor cells that are BRAFV600E/K and BRAFWT showed that, paradoxically, while PLX4032 inhibited ERK1/2 in the highly sensitive BRAFV600E/K, it activated the pathway in the resistant BRAFWT cells, via RAF1 activation, regardless of the status of mutations in NRAS or PTEN." (PMID 20149136, 2010). "Consistently, VEGF, histamine, and thrombin also promoted the migration of B16F10 melanoma cells through a monolayer of F/F, but not BRAF knockout endothelial cells, and this phenotype was rescued in BRAF/RAF1 knockout monolayers." (PMID 30828992, 2019). "Interestingly, although RAF-1 knockdown does not alter MST2 expression levels, it significantly reduces the expression of YAP and TAZ, thereby suppressing cell proliferation, migration, and invasion, while promoting apoptosis in four melanoma cell lines." (PMID 41550920, 2025).
melanoma (continued). "Sorafenib had only modest activity as a single agent in advanced melanoma and it did not appear to be more effective in the treatment of melanomas that are either WT or mutant at the BRAF gene, hence it may be targeting a kinase other than B-Raf in these melanomas (e.g., VEGFR or Raf-1)." (PMID 23085539, 2012).
breast cancer (106 papers, 2007 to 2026). A primary or metastatic malignant neoplasm involving the breast. "Like our study, a related study assessed the diagnostic and prognostic significance of RAF1 alongside miR-106a in breast cancer." (PMID 40727567, 2025). "The findings confirmed that both markers are crucial for early detection and management of breast cancer, further emphasizing RAF1′s diagnostic potential." (PMID 40727567, 2025). "We next examined the association of RAF1 mRNA expression with distant metastasis-free survival in HER2 (±) breast cancer samples." (PMID 38356266, 2024). "Coincidentally, a breast cancer study also indicated that dysregulation of the MAPK pathway due to RAF1 amplification is associated with poor outcomes and resistance to PD-1/PD-L1 therapy." (PMID 38111008, 2023). "The subgroup of patients carrying these alterations shows a worse prognosis; alterations in NF1 and RAF1 are associated with significantly reduced breast-cancer-specific survival in multivariate analysis." (PMID 36358725, 2022). "Sera and plasma of 30 normal women and 50 women with breast carcinoma were assayed for MiR-106a by RT-qPCR as well as levels of Hb, WBCs and platelets count and RAF-1 by solid phase enzyme-linked immunosorbent assay (ELISA)." (PMID 34837907, 2021). "The Rap1 signaling pathway is the main target of the Damnacanthus indicus C.F.Gaertn, and we found three overlapping genes (MAP2K1, PIK3CA, and Raf1) in the Rap1 signaling pathway associated with the breast cancer." (PMID 30906409, 2019). "The Raf-1 siRNAs and Raf-1 inhibitor GW5074 were used to inhibit Raf-1 activity to further observe the underlying mechanism of Gal-1 knockdown on MDR of breast cancer cells." (PMID 28212576, 2017). "In our study, we showed that oncogenic signaling by RAF1 is linked to the activation of the MEK/JNK pathway in metastatic breast cancer cells." (PMID 26649302, 2015). "We examined whether pimozide inhibits breast cancer by regulating RAF/ERK pathway and found that pimozide treatment caused downregulation of RAF1 phosphorylation in breast cancer cells." (PMID 38356266, 2024). "The triple interaction of TPH2 rs1386483 and rs1473473 as well as RAF1 rs3729931 increased breast-cancer risk by 20%, a dual interaction of MAPK8 rs10857561 and MAP2K1 rs1347069 by 15%, and MAPK8 rs10857561 alone by 11% (all observed at a prior probability of 0.01)." (PMID 37789226, 2023). "In this study, we found that RAF1 might be associated with a poor prognosis in breast cancer." (PMID 38356266, 2024). "The present study aimed to evaluate the correlation between MiRNA-106a gene expression and levels of Hb%, WBCs and platelets count as well as tumor marker proteins RAF-1 in a trial to check their early diagnostic and prognostic value which may help to understand their roles in breast cancer." (PMID 34837907, 2021). "Conversely, pharmacological inhibition of PDE8A restores cAMP/PKA-dependent suppression of Raf-1, diminishes Integrin α L function, and thereby reduces adhesion and metastasis in breast cancer cells." (PMID 41601682, 2026). "The result shows UISNet selected some important genes such as MAPK1, AKT1, RAF1, that have been proved related to breast cancer prognosis." (PMID 38418940, 2024). "ER2 (+) breast cancer cases with RAF1 protein and mRNA high expression had a shorter survival time (p = .022, p = .031)." (PMID 38356266, 2024). "The knockdown of RAF1 expression induced autophagy and apoptosis in breast cancer cells, consistent with the results of pimozide or sorafenib alone." (PMID 38356266, 2024). "We examined the expression of RAF1 in breast cancer and adjacent tissues by immunohistochemistry and found that RAF1 expression was related to HER2." (PMID 38356266, 2024). "The downregulation of CDK10 facilitates increased Raf-1 phosphorylation, resulting in increased Raf-1 activity and tamoxifen resistance in breast cancer cells." (PMID 38727267, 2024).
breast cancer (continued). "As such, a clinical trial (e.g., AZD6244) for a drug that inhibits RAF1-ERK signaling resulted in the inhibition of the progression of breast cancer through the eradication of CICs." (PMID 35955891, 2022). "Expression of MiR-106a gene can be used as a diagnostic and prognostic noninvasive biomarker which can stimulates breast cancer cell invasion and proliferation through downregulation of Raf-1 levels." (PMID 34837907, 2021). "Induced apoptosis and degradation of HSP70/HSP90 client proteins (HER2,Raf-1, Akt kinases) in breast cancer cells." (PMID 32121660, 2020). "The MAP2K1, PIK3CA, and RAF1 and especially Raf1 are all believed to be the common suppressors in the breast cancer." (PMID 30906409, 2019). "MiR-195 and miR-497 inhibited corresponding breast cancer cells proliferation and invasion via decreasing Raf-1, ERK, p-ERK expression levels." (PMID 29403024, 2018). "In conclusion, Gal-1 knockdown dramatically improved drug sensitivity of breast cancer by reducing P-glycoprotein (P-gp) expression via inhibiting the Raf-1/AP-1 pathway, providing a novel therapeutic target to overcome MDR in breast cancer." (PMID 28212576, 2017). "In breast cancer, miR-195-5p can increase the sensitivity of the cells to adriamycin treatment via Raf-1 inhibition." (PMID 28969047, 2017). "We have demonstrated that overexpression of a constitutive active Raf-1 mutant in ERa+ MCF-7 breast cancer cells (vMCF-7∆Raf1) resulted in constitutive activation of MAPK oncogenic signaling and enhanced tumorigenic properties in vivo." (PMID 29207686, 2017). "Next, ASSIGN was used to estimate the activation of each GFRN member (AKT, BAD, EGFR, HER2, IGF1R, KRAS (G12V), and RAF1) in 1119 breast cancer patient samples from TCGA and 55 samples from the ICBP panel of breast cancer cell lines." (PMID 28446242, 2017). "The level of miR-195 expression is inversely correlated with tumorigenesis and Raf-1 (rapidly accelerated fibrosarcoma) is a direct target of miR-195 and Raf-1 is overexpressed in many cancers including breast cancer." (PMID 27404381, 2016). "The induction of Raf-1 by lapatinib in a time-dependent manner was also found in human primary breast cancer cells from TNBC patients." (PMID 26513016, 2015). "The miR-195/497 cluster also functioned as a tumor suppressor by targeting RAF1/CCND1 in breast cancer." (PMID 24520312, 2014). "miR-195 was shown to inhibit cyclin D1 in HCC and breast cancer, CCND3 in glioblastoma, CDK4 in bladder cancer, CDK6 in HCC, E2F3 in HCC and glioblastoma, BCL-2 in breast and colorectal cancer, RAF1 in breast cancer, and GLUT3 in bladder cancer." (PMID 23335942, 2012). "In MCF-7 breast cancer cells, overexpression of the constitutively active Raf-1 resulted in resistance toward doxorubicin." (PMID 23316476, 2012). "Recently, miR-195 and miR-497 were shown to suppress breast cancer cell proliferation and invasion via targeting Raf-1 and CCND1." (PMID 22723898, 2012). "Recently MET has been examined in estrogen-receptor alpha positive (ERalpha+) MCF-7 breast cancer cells which overexpress activated Raf-1 and are more resistant to the chemotherapeutic drug doxorubicin than parental MCF-7 cells." (PMID 23455493, 2012). "The mitotic kinase Aurora-A promotes metastases by inducing EMT transition in ERalpha+ MCF-7 breast cancer cells which expressed constitutively-active Raf-1." (PMID 23455493, 2012). "We examined the relationship between RAF1 expression and prognosis in breast cancer patients." (PMID 38356266, 2024). "In the follow-up work, we will study the regulation of unknown regulatory factors by pimozide in breast cancer cells, resulting in the blockage of cross-linking between RAF1 and the Hippo pathway." (PMID 38356266, 2024).